ENSG00000260729 (novel protein)
Gene: Protein-coding gene on chromosome 15 (72,284,727 to 72,375,981, reverse strand). Ensembl gene ENSG00000260729.
Genetic constraint (gnomAD): Missense variants: 239 observed, 244.32 expected, observed/expected ratio (o/e) 0.98, 90% interval 0.88 to 1.09. Synonymous variants: 85 observed, 99.83 expected, observed/expected ratio (o/e) 0.85, 90% interval 0.71 to 1.02.